TNF (tumor necrosis factor)
Diseases named in the same sentence as TNF in open-access papers (continued):
Sharing a sentence is not in itself a finding about the gene and the disease.
Insulin resistance (continued). "Inflammatory markers (TNF-α, IL-1, IL-6) are associated with a reduction of AS160 activities, resulting in increased insulin resistance." (PMID 24098343, 2013). "Anti-TNF-α therapy has also shown to attenuate in insulin resistance in animal studies involving fructose-red rats." (PMID 23762871, 2013). "TNF-α is markedly upregulated in obese states and probably promotes insulin resistance by interfering with insulin receptor signalling." (PMID 23671875, 2013). "The proinflammatory cytokine TNF-α plays a pivotal role in the pathogenesis of insulin resistance by the impairment of insulin signal transduction in cells and animals." (PMID 23389304, 2013). "Biologic therapies, such as TNF-α antagonists, that block proinflammatory cytokines have beneficial effects on the insulin resistance that is often observed in patients with RA." (PMID 23431244, 2013). "Resistin, another adipokine, has been shown to have an insulin resistance-inducing effect and to induce inflammation via stimulation of TNF-α and IL-6 production by monocytes." (PMID 23598440, 2013). "Hepatic macrophages are a major source of proinflammatory mediators such as tumor necrosis factor-α (TNFα), interleukin-6, and reactive oxygen species, which are considered to accelerate hepatic steatosis and insulin resistance." (PMID 24349208, 2013). "TNF-α has been proposed as a link between adiposity and the development of insulin resistance, because the majority of type 2 diabetic subjects are obese." (PMID 23762871, 2013). "In cultured murine adipocytes, IL-6 production is strongly increased by TNF-α and induces insulin resistance by inhibiting glucose uptake and impairing insulin signaling and action." (PMID 24455420, 2013). "This study also showed that interleukin-10 (IL-10), produced by these Foxp3 Treg cells, inhibited tumor necrosis factor-alpha (TNFα)-induced expression of proinflammatory mediators and insulin resistance in 3T3-L1 adipocytes." (PMID 23671849, 2013). "In the same sense, in obese adolescents leptin has been shown to rise independently of the levels of insulin resistance and TNF-α." (PMID 23986664, 2013). "Several studies were also conducted to determine long-term effect of TNF-α antagonists on insulin resistance." (PMID 23431244, 2013). "Pro-inflammatory cytokines are strong contributors to increased insulin resistance, specifically TNF-α." (PMID 24101915, 2013). "Adipocytes regulate and mediate inflammatory cytokines such as tumor necrosis factor-α (TNFα) and IL-6, which, respectively, inhibit or enhance each other, contributing to insulin resistance." (PMID 23671865, 2013). "Effect of STZ- induced (50 mg.kg−1, 8 weeks) diabetes and daily oral administration of quercetin (50 mg.kg−1) on body weight, blood glucose, serum insulin, insulin resistance (IR) index, TNF-α, C-reactive protein (CRP), systolic BP." (PMID 23717483, 2013). "Especially in obese patients the systemic inflammation with serological findings of increased pro-inflammatory cytokines such as TNF-α and L-6 leads to TNF-α-induced insulin resistance and subsequently to a pre-diabetic state." (PMID 24010984, 2013). "High TNF-alpha concentrations and insulin resistance in endothelial cells have been reported to reduce the expression of the arginine recycling enzyme, argininosuccinate synthetase." (PMID 23320804, 2013). "As a result, South Asians have higher adipocyte surface areas and increased secretions of tumor necrosis factor α and free fatty acids, both of which can lead to insulin resistance." (PMID 22851968, 2012). "Elevated serum concentrations of C-reactive protein, interleukin IL-6, IL-8, and tumor necrosis factor (TNF)-α are observed in obese individuals with elevated insulin resistance." (PMID 23091306, 2012). "We found that following venom injection, TNF-α increases Map4k4 expression in adipose tissue, promoting insulin resistance." (PMID 22816003, 2012).
Insulin resistance (continued). "Overproduction of TNF-α in both adipose tissue and skeletal muscle contributes to insulin resistance." (PMID 22816003, 2012). "Increased ROS production is common to different models of cellular insulin resistance, including those induced by TNF-α, insulin and palmitate treatments." (PMID 22586466, 2012). "Increased TNF-α can exacerbate insulin resistance, which is normal in pregnancy; this favors the development of GDM." (PMID 22462002, 2012). "Our finding indicates that the hyperglycaemia and hyperinsulinemia induced by insulin-resistance correlated positively with the expression of TNF-α mRNA in an abdominal WAT depot." (PMID 23056223, 2012). "HCV infection promotes insulin resistance, mainly through increased tumor necrosis factor α (TNF-α), which inhibit insulin receptor and IRS-1 (insulin receptor substrate) tyrosine phosphorylation." (PMID 22675572, 2012). "Tumor necrosis factor alpha, was the first proinflammatory cytokine found to induce insulin resistance." (PMID 23065486, 2012). "Anti-TNF therapy resulted in significant improvement in insulin resistance/sensitivity and pancreatic beta cell function in RA patients with high baseline insulin resistance." (PMID 22691241, 2012). "Pro-inflammatory cytokines, particularly tumor necrosis factor-α (TNF-α), can enhance the serine phosphorylation of insulin receptor substrate-1, a crucial event in the induction of insulin resistance." (PMID 22880019, 2012). "Anti-TNF-α treatment apparently ablates insulin resistance via restoration of normal tyrosyl phosphorylation dependent insulin signaling." (PMID 22606220, 2012). "FFA have long been known to produce deleterious effects on pancreatic beta-cell function inhibiting insulin production and inducing insulin resistance whereas in parallel proinflammatory cytokines, such as TNF-α, alter insulin receptors." (PMID 22701480, 2012). "For instance, TNF-α an inducer of insulin resistance have been shown to directly affect the insulin receptor." (PMID 23272222, 2012). "TNF-α doesn't seem to correlate either with insulin resistance or with endothelial dysfunction in men with MS." (PMID 22558213, 2012). "TNF-α rapidly induces insulin resistance by stimulating free fatty acid (FFA) synthesis and secretion, which interferes with post insulin receptor signaling via altered phosphorylation of insulin receptor substrates." (PMID 23056469, 2012). "In pregnancy, TNF-α production in maternal adipose tissue is enhanced by the placental production of TNF-α, which makes it an important factor in the pathogenesis of insulin resistance and GDM." (PMID 22462002, 2012). "Adipose tissue is thought to directly exaggerate insulin resistance and to trigger inflammation by secreting adipokines such as IL-6 and TNF-α." (PMID 23155382, 2012). "Metformin reduced hepatic expression of TNF-α, a mediator of hepatic insulin resistance and necroinflammation, increased FFAs oxidation, and suppressed lipogenesis through AMPK activation." (PMID 23209914, 2012). "Adiponectin is an essential mediator in the regulation of insulin resistance and antiinflammatory effects through the inhibition of TNF-α and upregulation of the antiinflammatory cytokines." (PMID 22778500, 2012). "Data to support a role for TNF-α in the genesis of insulin resistance found in insulin resistant transgenic mice infected with hepatic C core protein." (PMID 23049551, 2012). "Adipose tissue secretes various cytokines including TNF-α, IL-6 and adipokines such as leptin and adiponectin involved in glucose metabolism and insulin resistance." (PMID 22816003, 2012). "Our findings for the effects of the TNF-α inhibitor etanercept and for Map4k4 expression strongly suggest that the venom-induced insulin resistance is TNF-α-dependent and was mediated at least in part by Map4k4 activation in adipose tissue." (PMID 22816003, 2012).
Insulin resistance (continued). "This would be similar to the exacerbation of insulin resistance in obese mice experimentally infected with C. pneumoniae that was mediated by circulating TNF-α released from the lung, the primary infection site." (PMID 23024776, 2012). "TNF mediates insulin resistance by inhibition of AKT activity through a ceramide-activated protein-phosphatase (PP) 2A." (PMID 22691241, 2012). "Evidence suggests that TNF-α induces adipocytes apoptosis and promotes insulin resistance by the inhibition of the insulin receptor substrate 1 signaling pathway." (PMID 22523672, 2012). "The answer to this question was provided by a study that has shown that TNF-α can induce insulin resistance in obese rodents and also that neutralization of TNF-α can decrease the insulin resistance with resulting increased peripheral uptake of glucose." (PMID 22792473, 2012). "Among patients with high insulin resistance at baseline, treatment with anti-TNF agents for 12 weeks resulted in significant improvement in insulin sensitivity as evidenced by reduction in the HOMA-IR and increase in the QUICKI indices." (PMID 22691241, 2012). "TNF-induced insulin resistance involves inhibition of AKT through a ceramide-activated protein-phosphatase (PP) 2A." (PMID 22691241, 2012). "We found that treatment with anti-TNF agents resulted in significant reduction in the HOMA-B index of pancreatic beta cell function in RA patients with high baseline insulin resistance." (PMID 22691241, 2012). "Taken together, our finding indicated that the hyperglycaemia and hyperinsulinemia induced by insulin-resistance correlated positively with the expression of TNF-α mRNA in an abdominal WAT depot." (PMID 23056223, 2012). "It has been shown that IL-6 suppresses the production of TNF-α, a cytokine involved in the pathogenesis of insulin resistance and CVD." (PMID 22272193, 2012). "After 12 weeks of anti-TNF therapy, patients with high insulin resistance demonstrated significant reduction in HOMA-IR (P < 0.001), HOMA-B (P = 0.001), serum triglycerides (P = 0.039), and increase in QUICKI (P < 0.001) and serum HDL-C (P = 0.022)." (PMID 22691241, 2012). "Anti-TNF therapy improved insulin sensitivity and reversed defects in the insulin signaling cascade in RA patients with active disease and high insulin resistance." (PMID 22691241, 2012). "Overproduction of TNF-α supports and even amplifies the inflammatory process leading to insulin resistance." (PMID 22701472, 2012). "High TNF-α levels can induce insulin resistance in animal models through the activation of I-kappa-B-kinase-β (IKKβ)/nuclear-factor-kappa-B (NF-κB) and Jun N-terminal kinase (JNK) pathways." (PMID 22792473, 2012). "In the present study, mouse FL83B cells were treated with tumor necrosis factor-alpha (TNF-α) to induce insulin resistance, and then co-incubated with a fraction from wax apple fruit extract (FWFE)." (PMID 22942720, 2012). "Parameters of liver steatosis, glutathione status, protein carbonylation, and fatty acid analysis were determined, concomitantly with insulin resistance and serum tumor necrosis factor-α (TNF-α), interleukin (IL)-1β, and IL-6 levels." (PMID 23082120, 2012). "Relevance of elevated serum IL-6, and TNF-α levels to insulin resistance and diabetes has been shown accordingly." (PMID 22792092, 2012). "As cytokines released from adipose tissue lead to insulin resistance and β-cell failure, increase of TNF-α and IL-1β expression is important in the pathogenesis of type 2 diabetes." (PMID 22844333, 2012). "The present study aimed to investigate the effect of a fraction from wax apple fruit extract (FWFE) on alleviating insulin resistance in TNF-α treated insulin resistant FL83B mouse hepatocytes." (PMID 22942720, 2012). "TNF-α contributes insulin resistance by blunting the insulin-stimulated tyrosine phosphorylation of IRS-1, inhibiting glucose uptake, and activating NFκB pathway." (PMID 22778500, 2012).
Insulin resistance (continued). "GTCs supplementation was also found to decrease plasma levels of insulin, TNF-α, and IL-6 in a rat insulin resistance model." (PMID 22312273, 2012). "We evaluated the outcome on insulin resistance and other metabolic parameters among 61 patients with active RA disease, after 12 weeks of treatment with anti-TNF agents." (PMID 22691241, 2012). "Currently, we suggest that TNF-α-induced insulin resistance is only indirectly involved in increased LYRM1 expression." (PMID 22110480, 2012). "TNFα plays a pivotal role in pain transmission, nerve degeneration and insulin resistance in diabetes related neuropathies." (PMID 22412941, 2012). "Recently, it has been shown that local generation of TNF-α in skeletal muscle acts paracrinally or autocrinally, inducing insulin resistance." (PMID 22359625, 2012). "IFNγ has an increasingly apparent role in regulating not only adipocyte cytokine secretion including TNFα but also insulin resistance and infiltration of T cells into obese adipose tissue." (PMID 22276186, 2012). "Abdominal subcutaneous tissue produces a variety of adipokines, such as TNF-α and IL-6, which has an important role in inflammation and insulin resistance via endocrine, paracrine, or autocrine signals." (PMID 21822486, 2012). "It has been known that elevated circulating levels of TNF-α and IL-6 in obese subjects play an important role in the development of insulin resistance." (PMID 23191980, 2012). "HF-induced insulin resistance is due, in part, to increases in macrophage infiltration and the local levels of TNFα and IL-6 in skeletal muscle and the subsequent deleterious effects of these cytokines on insulin signaling in muscle tissue." (PMID 22272317, 2012). "Since then similar findings of elevated TNF-α were also found in humans with increased insulin resistance and impaired glucose tolerance." (PMID 22792473, 2012). "Adipokines, e.g. TNFα, IL-6 and leptin increase insulin resistance, and consequent hyperinsulinaemia influences breast cancer progression." (PMID 21774820, 2011). "Increase in pro-inflammatory adipokines, such as TNF-α and IL-6, also leads to glucose intolerance and insulin resistance." (PMID 21569357, 2011). "In diabetic animals, TNF-α level was elevated and contributed to insulin resistance, whereas limited data is available on the effects of TNF-α on diabetic blood coagulation." (PMID 23554679, 2011). "hyperinsulinemia and insulin resistance appear to augment the inflammatory effects of TNFα on VCAM-1 expression and NFκB translocation, both of which are markers of inflammation in the vasculature." (PMID 22093181, 2011). "There is evidence that insulin resistance results from the proinflammatory cytokines actions released from the adipose tissue, such as TNF-α and IL-6." (PMID 21352586, 2011). "In cancer patients, insulin resistance is thought to be mediated by an acute phase response that is triggered by pro-inflammatory cytokines such as tumor necrosis factor (TNF)-α and IL-6." (PMID 22029671, 2011). "Further work demonstrated that TNF attenuated insulin-stimulated tyrosine phosphorylation of the insulin receptor and IRs1 in muscle and adipose tissues, thus promoting insulin resistance." (PMID 21960997, 2011). "In this context, numerous substances, mainly released by adipose tissue such as tumor necrosis factor-alpha (TNF-α) are closely linked to each other and are thought to contribute to peripheral insulin resistance." (PMID 21886908, 2011). "Exposure of endothelial cells to palmitate, glucose, TNF-α all mediators of insulin resistance, results in activation of NF-κB and increased expression of adhesion molecules, an early marker for atherosclerosis." (PMID 22216328, 2011). "On the other hand, repeated administration of palmitoleic acid down-regulated mRNA expressions of TNFα and resistin, the adipocytokines that have been demonstrated to contribute to insulin resistance." (PMID 21774832, 2011).
Insulin resistance (continued). "Insulin resistance can be generated by decreased adiponectin secretion and increased TNF-α secretion." (PMID 21799697, 2011). "On the other hand, the administration of recombinant human vaspin improved insulin sensitivity and glucose tolerance, and reverses the expression of those genes that can promote insulin resistance such as leptin, resistin and TNF-α, in diet-induced obese mice." (PMID 21526992, 2011). "The question remains, however, does insulin in the context of insulin resistance/hyperinsulinemia exacerbate or mitigate the existing conditions of TNFα-stimulated VCAM-1 expression?" (PMID 22093181, 2011). "Studies have reported that pro-inflammatory cytokines, tumor necrosis factor (TNF)-α and interleukin (IL)-6, are associated with an increased hepatic C-reactive protein (CRP) synthesis, inflammation, and insulin resistance in humans and animals." (PMID 21554710, 2011). "Tumor necrosis factor alpha (TNF-α) was found to be a crucial component of the pro-inflammatory cytokines, mainly produced by macrophages and adipocytes, and can induce insulin resistance in T2DM." (PMID 21494616, 2011). "Proinflammatory mediator TNFα is known to promote insulin resistance in which serine phosphorylation of insulin receptor substrate (IRS) is encouraged." (PMID 21941675, 2011). "During stress, the generation of elevated amounts of TNF-α impairs insulin signaling, leading ultimately to insulin resistance." (PMID 19884114, 2011). "Metformin, an antidiabetic agent, suppresses the production of TNFα, a known factor for insulin resistance." (PMID 21941675, 2011). "Although TNFα is known to be involved in the development of insulin resistance in both adipose tissue and the liver, it was only significantly upregulated in adipose tissue." (PMID 21978410, 2011). "POP can increase secretion of tumor necrosis factor alpha (TNF-α), which plays an essential role in development of insulin resistance." (PMID 21556177, 2011). "Similar to our results, it is reported that the adipose tissue secretes inflammatory cytokines such as TNF-α by inducing insulin resistance and upregulating the expression of other inflammatory mediators." (PMID 20953409, 2010). "TNF-α activates NF-κB and other inflammatory pathways involved in the etiology of insulin resistance and Type 2 diabetes." (PMID 20808947, 2010). "The expression of TNF-α, IL-6, MCP-1, and leptin is upregulated in the adipose tissue of obese mice which is closely associated with insulin resistance." (PMID 21403905, 2010). "Onset of intestinal inflammation precedes diet-induced increases in body weight, fat mass and insulin resistance and degree of TNF-α induction strongly correlates with diet-induced increases in weight, adiposity, plasma glucose, and insulin." (PMID 20808947, 2010). "Among the proinflammatory molecules, TNF-α has been proposed to be the key link between obesity and insulin resistance." (PMID 20426802, 2010). "Of these, TNF-α has been shown to alter adipogenesis and to inhibit insulin signalling in mice suggesting that low-grade inflammation induces insulin resistance." (PMID 21179199, 2010). "TNFα can induce insulin resistance and this is probably a part of the explanation why insulin resistance, endothelial dysfunction, and atherothrombosis are so closely related." (PMID 20634940, 2010). "A strong link exists between increased inflammatory cytokines, such as tumor necrosis factor-alpha (TNF-α) and interleukin-6 (IL-6), and insulin resistance in obese individuals." (PMID 20877574, 2010). "β-arrestins have also been reported to contribute to insulin resistance by mediating a TNFα-induced inflammatory pathway." (PMID 20858278, 2010). "TNF α, a significant mediator in insulin resistance, affects the activity of tyrosine kinase in insulin receptors." (PMID 20953409, 2010).